IL6 (interleukin 6)
Diseases named in the same sentence as IL6 in open-access papers (continued):
Sharing a sentence is not in itself a finding about the gene and the disease.
Neonatal sepsis (continued). "Hence, for the early diagnosis IL-6 (from cord blood or peripheral neonatal blood) and later repetitive measurements of CRP seem to be helpful in the diagnosis of neonatal sepsis considering the clinical aspect of the neonate, its gestational age, maternal risk factors, and the time of sampling." (PMID 35345614, 2022). "The clinical identification and diagnosis of neonatal sepsis is confirmed by blood culture, and the assessment of acute phase reactants includes C-reactive protein (CRP), procalcitonin, presepsin, and inflammatory mediators such as interleukin-6 (IL-6) and tumor necrosis factor-alpha (TNFα)." (PMID 34900858, 2021). "IL-6 is not considered a “gold standard” biomarker to have a very short half-life, approximately 100 minutes in patients with meningococcal infection; additionally, the circulating levels decrease or return to basal levels 24 hours after appropriate treatment in late-onset neonatal sepsis." (PMID 25614712, 2014). "Therefore, we excluded all cases of neonatal sepsis and STORCH infections, as well as neonates requiring any type of ventilatory support in the delivery room, who might have elevated baseline IL-6 levels—a situation that might impact the evaluation of the behavior of IL-6." (PMID 25799377, 2015). "In cases of neonatal sepsis, Fan and Yu (2012) did not recommend the isolated use of inflammatory markers CRP, PCT, interleukin-8 (IL-8), TNF-α and interleukin-1 beta (IL-1β); although IL-6 was rated as superior in relation to the majority of markers, it should not be used in isolation." (PMID 34846061, 2022).
acute coronary syndrome (105 papers, 2007 to 2025). Signs and symptoms related to acute ischemia of the myocardium secondary to coronary artery disease. "Acute coronary syndrome patients in the highest quartile of IL-6 have a higher risk of cardiovascular events and death." (PMID 37887854, 2023). "Those MMPs can be activated by a plethora of cytokines (e.g., TNF-alpha, INF-γ, IL-1, and IL-6), thus diminishing the cohesion of the atherosclerotic plaque and consecutively increasing the risk of acute coronary syndromes." (PMID 35888173, 2022). "Synthesis of IL-6 is induced rapidly in the ischemic-reperfused myocardium, and IL-6 has been associated with acute coronary syndrome." (PMID 33996944, 2021). "Interleukin-6 is considered to increase the risk of adverse events after an acute coronary syndrome." (PMID 34884196, 2021). "The present investigation was developed for the exploration of the association between IL-6 levels and acute coronary syndrome (ACS) findings upon angiographic evaluation." (PMID 34861824, 2021). "The GG variant of the promoter polymorphism of IL-6 was also reported to be the significant predictor of early death after acute coronary syndrome in elderly males." (PMID 30635365, 2019). "It has been also demonstrated that IL-6 levels in acute coronary syndrome are associated with prothrombotic plasma thrombin generation profile." (PMID 28429138, 2017). "TNF-α has been implicated in myocardial dysfunction resulting from acute coronary syndrome and high levels of IL-1 and IL-6 have been associated with subclinical atherosclerosis." (PMID 25374442, 2014). "Alwi and coworkers indicated that increased circulating IL-6 levels was associated with pathophysiology of acute coronary syndrome." (PMID 24363620, 2013). "Polymorphisms of proinflammatory cytokines, such as IL-6 -174 G > C, have also been associated with acute coronary syndrome (ACS), resulting in higher risk of death among elderly ACS male patients." (PMID 22408428, 2012). "IL-6 was also associated with plaque instability in acute coronary syndrome (ACS)." (PMID 34356982, 2021). "The researchers concluded that IL-6 might be helpful in risk stratification in patients after an acute coronary syndrome." (PMID 34356982, 2021). "Post-acute coronary syndrome risk also relates to IL-6 concentrations in plasma." (PMID 33924019, 2021). "Interestingly, our study found a correlation between 2-AG levels and IL-6, the latter of which has recently been demonstrated to be associated with an elevated risk of major adverse cardiovascular events after an acute coronary syndrome." (PMID 31887202, 2019). "Whether the short-term increases in IL-6 and fibrinogen observed in this study actually lead to an increased risk for an acute coronary syndrome, however, remains to be shown." (PMID 17637925, 2007). "There is clinical evidence supporting the prognostic value of CRP and IL-6 in acute coronary syndrome; however, the relevance of IL-1β and TNF-α as prognostic markers in this context remains uncertain." (PMID 40168324, 2025). "IL‐6 is a prominent proinflammatory cytokine, found to be increased in patients after acute coronary syndrome." (PMID 39853914, 2025). "Regarding the IL-6 concentration in acute coronary syndrome patients, we documented a higher median concentration in our cohort compared with previous studies." (PMID 36860987, 2023). "Among these, C-Reactive Protein (CRP) and Interleukin-6 (IL-6) are both significantly upregulated in acute coronary syndrome." (PMID 38140053, 2023). "Increased concentrations of C-reactive protein (CRP), amyloid A, or interleukin 6 (IL-6) were observed in a significant percentage in patients with acute coronary syndromes." (PMID 36071866, 2022). "The interleukin-6 (IL-6) signaling pathway is a crucial mediator of inflammation in the lesions, and elevated plasma IL-6 in patients with acute coronary syndrome is currently the most powerful predictor of increased mortality in both short and long terms." (PMID 35872917, 2022).
acute coronary syndrome (continued). "Based on the subgroup analysis, the risk of coronary revascularization was reduced by 31% in the group of targeting the central IL-6 inflammatory signaling pathway and decreased by 37% in patients with acute coronary syndrome group." (PMID 35246052, 2022). "Based on our findings, it seems reasonable to suggest that the interaction between Lp(a) and α7-nAChR significantly increases IL-6 levels, which ultimately prove critical during acute coronary syndrome." (PMID 35096275, 2022). "IL-6 has procoagulant effects, and elevated levels have been reported among patients with acute coronary syndromes." (PMID 36028849, 2022). "For example, in the setting of acute coronary syndrome, colchicine was effective in suppressing interleukin IL-1b, IL-18 and IL-6, which was attributed to inflammasome inhibition." (PMID 36128202, 2022). "This study aimed to explore the relationship between plasma interleukin 6 (IL-6) levels, adverse cardiovascular events, and the severity of acute coronary syndrome (ACS)." (PMID 34231707, 2021). "Circulating Th17-related cytokines (IL-17, IL-6, IL-23) increased at the onset of acute coronary syndrome." (PMID 35087531, 2021). "In another study, patients in the acute phase of TTS had higher concentrations of interleukins 2, 4, 10, TNF-α, IFN-γ, and EGF, but lower levels of interleukin 6 compared to individuals with acute coronary syndrome." (PMID 34738019, 2021). "IL-6 levels have been already described as predictors of mortality in acute HF and acute coronary syndromes as well as chronic HF in some studies." (PMID 33535417, 2021). "It was shown that IL-6 is an indicator of the severity of atherosclerotic disease and myocardial damage during acute coronary syndrome." (PMID 31739518, 2019). "This suggests possible prognostic benefits of long-time observation of IL-6 level after the acute coronary syndrome." (PMID 31739518, 2019). "An increasing number of experimental observations suggest that IL-6 has a central role in the pathogenesis of several ischemic cardiovascular disorders, including unstable angina and acute coronary syndromes." (PMID 25333814, 2015). "The levels of TnI (marker of heart cardiac damage in acute coronary syndromes) and IL-6 (marker of inflammation) were measured in perfusates to determine cardiac tissue injury." (PMID 25961016, 2015). "Longitudinal studies have demonstrated that Interleukin 6 (IL-6) is a better predictor of CHF after acute coronary syndrome (ACS) than C-reactive protein (CRP), and that it is also an independent predictor of cardiovascular mortality." (PMID 25100442, 2014). "Evidence indicates that angiotensin II and IL-6 play a role in the pathogenesis of acute coronary syndrome." (PMID 25762441, 2014). "Several other biomarkers, e.g. C-reactive protein (CRP) and interleukin 6 (IL-6), have been identified also to indicate acute coronary syndrome (ACS)." (PMID 24313641, 2013). "A number of reports have described high IL-6 levels in acute coronary syndromes indicating evolving role of inflammatory markers in myocardial ischemiareperfusion." (PMID 23984427, 2013). "The effect of other acute phase reactants such as TNF, CRP and IL6 in prognosis of acute coronary syndromes is also known." (PMID 22811936, 2012). "IL-6 is increased in patients with acute coronary syndromes and stable CAD leading to an increased cardiovascular event rate." (PMID 23028694, 2012). "Interleukin-6 (IL-6) is a pleotropic pro-inflammatory cytokine that modulates the development of acute coronary syndromes (ACSs), partly by destabilizing coronary atherosclerotic plaques." (PMID 21245598, 2011). "Both vWF and IL-6 are released into the plasma during acute coronary syndromes and are predictive of adverse outcomes." (PMID 20822968, 2010).
acute coronary syndrome (continued). "Ongoing efforts are undertaken in an attempt to identify and validate additional cardiac biomarkers, for example, interleukin-6, soluble CD40L, and C-reactive protein, in order to further risk stratify patients with acute coronary syndrome." (PMID 19578513, 2008). "The degree of elevation of IL-6 portends a poorer prognosis after acute coronary syndromes." (PMID 37259918, 2023). "Increased levels of IL-6 stimulate the liver to synthesize and secrete CRP, which functions as a pro-atherosclerotic factor and serves as a risk marker for mortality from acute coronary syndrome (ACS) after 30–90 days." (PMID 36294425, 2022). "Moreover, colchicine administration contributed to the reduction in IL-1β, IL-18, and IL-6 in patients with acute coronary syndrome." (PMID 34440608, 2021). "IL-6 is expressed by many cell types, predominantly acts in a pro-inflammatory manner by mediating the acute phase response and has been associated with MACE in patients with acute coronary syndrome." (PMID 33604561, 2020). "Some researchers suggest that IL-6, a pro-inflammatory cytokine, may be a marker for lesion instability and better estimate the risk of acute coronary syndrome, which we did not evaluate." (PMID 39859253, 2025). "Importantly, IL-6 levels tend to rise during acute coronary syndromes." (PMID 38892840, 2024). "Notably, IL6/IL10 imbalance has been previously associated with incidence and severity of CV events in patients with acute coronary syndrome while it has been demonstrated that the overexpression of IL10 exerts an inhibitory effect on the atherosclerotic plaque formation." (PMID 35178353, 2022). "IL-1 and IL-6 together may contribute to the pathogenesis of acute coronary syndrome." (PMID 23028694, 2012). "In patients with acute coronary syndrome (ACS), Il6 serves as a critical biomarker for assessing both the severity of coronary artery disease (CAD) and the risk of mortality." (PMID 41347019, 2025). "Nicorandil suppresses the inflammatory cytokines IL-1β, IL-1, IL-6, IL-10, IL-18, IL-19 and TNF-α in acute coronary syndrome patients." (PMID 34595611, 2023). "We aimed to compare the efficacy between clopidogrel and ticagrelor in patients with acute coronary syndrome (ACS) after percutaneous coronary intervention (PCI) and their effects on IL-6." (PMID 32461931, 2020). "Along with other inflammatory markers, namely interleukin 6 (IL-6) and C-reactive protein (CRP), the level of hGIIA sharply increases during the first four days after acute coronary syndrome (ACS)." (PMID 32998383, 2020). "In clinical studies, elevated plasma MIF levels in patients with acute coronary syndrome also correlated with increased inflammatory markers such as C-reactive protein (CRP) and IL-6." (PMID 24098445, 2013). "Our analysis of the MIRACL study shows a strong relationship between early levels of CRP and the closely related markers of IL‐6 and SAA with death following an acute coronary syndrome." (PMID 23525424, 2013). "Statins were also shown to confer rapid benefits in patients with acute coronary syndrome by blocking pathologic factors such as CRP, tissue factor, IL-1, IL-6, and other pro-inflammatory cytokines." (PMID 23950953, 2013). "Another report showed that ticagrelor could reduce interleukin-6 (IL-6) and tumor necrosis factor-α (TNF-α) levels in diabetic patients with acute coronary syndrome (ACS)." (PMID 36684601, 2022). "On univariate analyses, baseline CRP (P=0.006), SAA (P=0.012), and IL‐6 (P<0.001) were related to death, but not to recurrent nonfatal acute coronary syndromes." (PMID 23525424, 2013). "In studies of acute coronary syndrome (ACS), colchicine has been shown to prevent NLPR3 inflammasome-induced caspase-1 activation, leading to decreased levels of interleukin IL-1b, IL-18, and IL-6 and CRP and a reduction in mortality from major cardiovascular events." (PMID 33133323, 2020).
acute coronary syndrome (continued). "Administration of calcitriol in patients with non-ST-segment elevation acute coronary syndromes undergoing elective PCI can attenuate the increase in serum inflammatory biomarkers in the serum (hs-CRP and hs-IL-6) and thus decrease the inflammatory reaction caused by PCI." (PMID 32802107, 2019). "The most tempting hypothesis might be that systemic inflammation largely driven by IL-6 and reflected by elevated CRP stimulates the activation of procoagulant mechanisms, leading to the enhanced thrombin formation, as it was shown in subjects with acute coronary syndrome." (PMID 28429138, 2017).
Anorexia (105 papers, 2009 to 2025). Lack of desire to eat (loss of appetite). "JAKi effectively treated cancer‐associated anorexia and adipose wasting in mice by targeting Interleukin 6 and leptin metabolism." (PMID 39564906, 2025). "The data showed that exposure to DON and its congeners at 2.5 mg/kg BW significantly elevated plasma IL-18 and IL-6 levels associated with toxin-induced anorexia." (PMID 39691381, 2024). "Serum concentrations of inflammatory biomarkers and cancer-related symptoms are related, and one study showed that interleukin-6 and C-reactive protein concentrations were associated with anorexia; however, interleukin-1ra was associated only with fatigue." (PMID 36407065, 2022). "The pathogenesis of inflammation-associated anorexia induced by cisplatin is unclear, and the role of IL-6 needs further investigation, as IL-6 was also shown to be highly elevated in both anorexia and obese patients." (PMID 35215322, 2022). "Often as part of a pro-inflammatory state, anorexia is associated with raised levels of interleukin-6 (IL-6) and C-reactive protein (CRP) in people with cancer." (PMID 33510313, 2021). "Aberrant IL-6 is involved in the regulation of sickness behavior (e.g., anorexia and lethargy) and directly linked to host morbidity." (PMID 33584608, 2021). "A number of cytokines have been previously linked to anorexia, including IL-6, TNF-α, CXCL8, IL-1β, IL-18, IL-2, and IFN-γ." (PMID 32071269, 2020). "Cachexia is distinct from starvation or malabsorption and can be accompanied by anorexia, elevated inflammatory cytokines (IL-1, IL-6 and TNF-α), loss of fat and insulin resistance." (PMID 30379866, 2018). "One potential cause of DON-induced anorexia is the induction of proinflammatory cytokines, including IL-1β, IL-6, and TNF-α, which have been previously shown to cause sickness behavior in humans and experimental animals." (PMID 26492270, 2015). "Potent anti-inflammatory effects of ghrelin were reported on the expression of IL-1β, IL-6, and TNFα in the liver, spleen, lungs, and mesenteric lymph nodes of LPS-treated mice associated with an attenuation of the LPS-induced anorexia." (PMID 26681840, 2015). "Additionally, pro-inflammatory cytokines such as IL-6 released from inflammatory cells cause anorexia, decreased dietary protein intake, and further hypercatabolism." (PMID 40648869, 2025). "Moreover, the temporal relationship between the expression of IL-18 and IL-6 was consistent with the anorexia caused by these mycotoxins." (PMID 39691381, 2024). "The release of pro-inflammatory cytokines, including TNF-α, IL-6, and IL-1, is provoked by cancer cells, which sets off a chain reaction that results in weight loss by causing the breakdown of skeletal muscle and adipose tissue as well as anorexia." (PMID 38466657, 2024). "It is also known that high level of cytokines TNFα, IL-6, and IL-2 are associated with a decrease in food intake and may contribute to anorexia." (PMID 32297262, 2020). "Classical gut barrier function enhancers, such as the GLP-2 analogue teduglutide and F. prausnitzii, were unsuccessful to restore this gut barrier function, whereas IL-6 antibody improves the gut barrier function and the microbial dysbiosis, as well as muscle atrophy, anorexia and body weight loss." (PMID 29719601, 2018). "Finally, IL-6 plays a pivotal role in cancer cachexia and the hypercatabolic state produced by this cytokine causes several symptoms such as anorexia, lowered serum albumin, a reduction in hemoglobin and a decrease of body mass index." (PMID 28927416, 2017). "A potential biological role for this metabolic pathway may be to suppress immunological damage to inflamed, non-infected tissues since many inflammatory conditions are associated with anorexia, high IL-6 levels, and elevated serum glucocorticoids." (PMID 27829137, 2016). "It is known that IL-6 causes anorexia, which would lead to decreased protein substrate." (PMID 23938060, 2013).